BRCA1 (BRCA1 DNA repair associated)
Diseases named in the same sentence as BRCA1 in open-access papers (continued):
Sharing a sentence is not in itself a finding about the gene and the disease.
breast cancer (continued). "We demonstrate that TOP1 and CDH3 are closely associated to BRCA1-deficient breast cancer." (PMID 27566577, 2016). "Therefore, we reasoned that parsing of breast cancers based on BRCA1 related measurements that led to the exclusion of most HR+ tumors and inclusion of only part of the TNBCs were likely to enrich for BRCA1 deficiency." (PMID 27077368, 2016). "This was higher than the germline BRCA1/2 mutation rates (2.2%) previously reported in a cohort of 645 unselected Chinese breast cancer women, and than that (3.0%) in 471 unselected Korea breast cancer patients using less sensitive methods." (PMID 27257965, 2016). "Approximately 60% of patients with BRCA1-associated breast cancer treated with neoadjuvant chemotherapy with cisplatin obtain a pathologic complete response (pCR) whereas a sizable percentage of such patients do not experience pathological complete response (non-pCR)." (PMID 27626685, 2016). "Inverse association between methylation of RASSF1 and BRCA1 loci and lower level of vitamin B12 is translated to clinical setting and it could be a useful public health strategy to decrease the risk of breast cancer." (PMID 27775595, 2016). "Statistical analysis of the methylation profiles of FOXO3 promoter in these familial breast cancers revealed that FOXO3 methylation levels were significantly higher in BRCA1-mutated tumours, compared with BRCA2-, BRCAx- and BRCA2/x-mutated tumours (P=0.019, P=0.053 and P=0.026, respectively)." (PMID 27043660, 2016). "Collectively, these data provide evidence that FOXO3 is methylated in basal subtype breast cancers, where BRCA1 is either mutated or depleted, highlighting the importance of BRCA1 in promoting FOXO3 expression through suppressing FOXO3 methylation in luminal breast cancers." (PMID 27043660, 2016). "Also, we found a BRCA1 founder mutation (c.981_982del), which was previously reported in Southern Chinese breast cancer patients." (PMID 27257965, 2016). "This association, which did not vary by estrogen receptor (ER) status, was one of the most significant associations found for breast cancer risk in Breast cancer 1 (BRCA1) mutation carriers so far, and the association was predominantly found in carriers with ER-negative (ER-(-)) breast cancer." (PMID 27459855, 2016). "Among different molecular subtypes, germline BRCA1/2 P/LP variants were preferentially detected in the patients with triple-negative (14/70; 20.0%) and Luminal B (21/290; 7.2%) breast cancer, as compared to the patients of Luminal A (1/60; 1.7%) and HER2 positive (1/67; 1.5%)." (PMID 27257965, 2016). "Hence, these data demonstrate that the ectopic expression of full length BRCA1 resulted in decreased sensitivity towards PB in BRCA1 mutated breast cancer cells." (PMID 27220670, 2016). "However the prognosis for BRCA1-associated breast cancer remained serious despite early mammography surveillance." (PMID 27087880, 2016). "Thus, even in cases of early onset breast cancer (≤35 years old), Uzbek women with the BRCA1 mutation would have already had children; therefore, they would have transmitted the mutation to the next generation." (PMID 29138730, 2016). "Results might be pivotal for registration of olaparib as standard first line treatment in advanced BRCA1- or BRCA2-mutated breast cancer." (PMID 27323902, 2016). "However, 15 of the 19 risk loci that reached genome-wide significance for ER-negative disease in the meta-analysis showed some evidence of association (P<0.05) with breast cancer risk for BRCA1 mutation carriers using a retrospective likelihood analysis." (PMID 27117709, 2016). "Most of BRCA1-deficient breast cancer are triple-negative and basal-like." (PMID 26848770, 2016). "The breast cancer susceptibility protein BRCA1 is an important tumour suppressor in breast cancer." (PMID 27043660, 2016).
breast cancer (continued). "Using PCR, PAGE, Sanger sequencing, and statistical analyses, we compared VNTR genotypes in the XRCC5 promoter between healthy individuals and three types of familial breast cancer cases: mutated BRCA1 (BRCA1+), mutated BRCA2 (BRCA2+), and wild-type BRCA1/BRCA2 (BRCAx)." (PMID 27148484, 2016). "Thus, this study has potential important diagnostic and therapeutic implications for BRCA1 functional deficient breast cancer." (PMID 27043660, 2016). "The BRCA-1 gene for example and some of its interaction partners are associated with breast cancer." (PMID 27863482, 2016). "Mutations in the BRCA1/2 tumour suppressors are linked to familial predisposition to breast cancer." (PMID 26927176, 2016). "Hierarchical cluster analysis showed that the mapped mRNA transcripts could separate the majority of the BRCA1/2 -deficient breast carcinomas from the majority of sporadic breast carcinomas." (PMID 27566577, 2016). "Therefore, we here applied immunohistochemistry for verification of increased expression of TOP1 and CDH3 in BRCA1-deficient breast carcinomas." (PMID 27566577, 2016). "In addition, it has been reported that the expression of BRCA1 is associated with platinum-resistance in ovarian carcinomas and chemoresistance in breast carcinomas." (PMID 27643881, 2016). "However, mutations in the two major breast cancer susceptibility genes BRCA1 and BRCA2 explain only 15–20% of all familial BC/OC cases." (PMID 27504877, 2016). "We assessed promoter methylation of breast cancer susceptibility gene 1 (BRCA1) and 17 Beta Hydroxysteroid Dehydrogenase Type 1 (17βHSD-1) in normal and cancer breast tissues of forty sporadic breast cancer (BC) cases using restriction enzyme based methylation-specific PCR (REMS-PCR)." (PMID 27413552, 2016). "One of these compounds, adenosine 5’-monophosphate (A5MP), selectively inhibited the growth of BRCA1-deficient HCC1937 breast carcinoma cells (adenosine was added to the cells and phosphorylated intracellular), even though that RAD52 does not have a nucleotide binding site." (PMID 27649245, 2016). "Similarly, an independent association of CDH3 expression for BRCA1/2-related breast carcinomas was found (adjusted OR 2.44; 95% CI, 1.08–5.49, p = 0.032)." (PMID 27566577, 2016). "Potential GxG associated with breast cancer risk in BRCA1/2 mutation carriers." (PMID 25830658, 2015). "Breast cancer screening guidelines have been delineated for the general population and for women with known genetic risk factors for breast cancer (i.e. BRCA1 and PTEN syndromes) to decrease mortality through early diagnosis; however, there are currently no such guidelines for NF1 patients." (PMID 25885768, 2015). "Germline pathogenic mutations in BRCA1 increase risk of developing breast cancer." (PMID 26727311, 2015). "For this purpose, we sequenced the complete coding and flanking regulatory regions of PALB2 from constitutional DNA of 152 patients with hereditary predisposition to breast cancer, all previously employed to study the distribution of germline mutations in BRCA1, BRCA2." (PMID 26489409, 2015). "Mutations of the BRCA1 gene confer a high risk for breast cancers." (PMID 25797244, 2015). "Previous studies consistently showed that approximate 10–15% of breast cancers have family history of the disease, but only 5% of them could be explained by the rare but highly penetrant mutations in BRCA1/2." (PMID 25756203, 2015). "In this reported case, there were clinical findings concerning both primary mammary carcinoma (clinically palpable breast mass, family history of breast cancer and BRCA1 mutation, and recent benign pleural biopsy) and malignant mesothelioma (history of asbestos exposure and pleural thickening)." (PMID 26448888, 2015). "Additionally, we observed different associations of rs3803662 with breast cancer risk based on different ER subtype and BRCA1/BRCA2 mutation carriers." (PMID 26239137, 2015).
breast cancer (continued). "A BRCA1 mutation was found in 18.4 % of women diagnosed with breast cancer at/or under the age of 40 compared to 11.2 % of women diagnosed at a later age; a BRCA2 mutation was found in 4 % of women diagnosed at/or under the age of 40 compared to 6.5 % of women diagnosed at a later age." (PMID 26183948, 2015). "Breast cancers arising in BRCA1 mutation carriers frequently showed low levels of 53BP1 expression." (PMID 27462418, 2015). "In this study, the entire coding sequence of the CHEK2 gene was screened for mutation on 59 breast cancer patients who were non-BRCA1 and BRCA2 mutation carriers and two previously reported missense mutations, p.I160M and p.R180C were identified in two unrelated breast cancer patients." (PMID 25629968, 2015). "Importantly, there is evidence that tamoxifen decreases risk of primary breast cancer as well as contralateral breast cancer for BRCA1 and BRCA2 mutation carriers." (PMID 26496879, 2015). "Patients with an established diagnosis of breast cancer found to have a BRCA1 or BRCA2 mutation also may experience feelings of worry." (PMID 26557407, 2015). "However, in patients with a suggestive personal and/or family history, a specific predisposing mutation in the breast cancer susceptibility gene-1 (BRCA1) or in the breast cancer susceptibility gene-2 (BRCA2) is identified in only fewer than 30% of cases." (PMID 26312763, 2015). "In this paper we show that OPG, which is the physiological antagonist of RANKL (a factor known to be crucially involved in breast carcinogenesis), is low in women who have inherited a gene mutation (i.e. in BRCA1 or 2) which puts them at extremely high risk of developing breast cancer." (PMID 26629528, 2015). "Although germline mutations in BRCA1 account for only 5% of breast cancer cases, silencing of BRCA1 by promoter hypermethylation and other mechanisms may contribute to ≤30% of sporadic breast cancers." (PMID 25975349, 2015). "We screened the RAD51, XRCC3, and XRCC2 genes for germline variation in familial BRCA1/2-negative breast or ovarian cancer patients in order to evaluate the role of these genes in breast cancer predisposition in Finland and to identify putative recurrent founder mutations." (PMID 25918678, 2015). "Interestingly, hereditary BRCA1-mutations appears to primarily predispose for the development of basal-like breast cancers, indicating that BRCA1 dysfunction is a potent driver of basal-like tumorigenesis." (PMID 26670335, 2015). "BRCA1 is a DNA repair-associated gene that, when mutated, contributes to familial breast cancer." (PMID 26170234, 2015). "Breast cancer development in BRCA1/2 mutation carriers is a net consequence of cell-autonomous and cell nonautonomous factors which may serve as excellent targets for cancer prevention." (PMID 26629528, 2015). "Family history was significant for breast cancer and BRCA1 mutation positivity in two siblings; the patient's own BRCA status was unknown." (PMID 26448888, 2015). "The two most commonly studied breast cancer susceptibility genes are BRCA1 and BRCA2." (PMID 25692038, 2015). "Conversely, an interaction between rs299290 and rs11649877 (3’ region of TUBG1) could increase breast cancer risk in both BRCA1 and BRCA2 mutation carriers (HRs = 1.33 and 1.21, respectively)." (PMID 25830658, 2015).
breast cancer (continued). "Some evidence has suggested that breast-feeding may reduce breast cancer risk even among women at highest risk of breast cancer, specifically BRCA1 mutation carriers, who tend to develop ER-negative tumors and have elevated CBC risk." (PMID 26751177, 2015). "In total, 108 South African breast cancer patients underwent mutation screening using a Next-Generation Sequencing (NGS) approach in combination with Multiplex Ligation-dependent Probe Amplification (MLPA) to detect large rearrangements in BRCA1 and BRCA2." (PMID 26577449, 2015). "Additionally, CNVs significantly associated with breast cancer risk have been previously reported in the adjacent 17q21 region, at BRCA1." (PMID 26152678, 2015). "Additionally, our analysis demonstrated that there were significant relationships between elevated risk of breast cancer and BRCA1/2 mutation carriers for rs3803662." (PMID 26239137, 2015). "The current study aimed to investigate whether TRs may be specifically expressed in BRCA1 associated cancer cases and whether they are of prognostic significance in these patients as compared to sporadic breast cancer cases." (PMID 26029931, 2015). "This, in turn, decreases BRCA1 expression and increases the risk of breast cancer." (PMID 26442220, 2015). "The 5382insC mutation of BRCA1 is a frequent germline mutation in Ukrainian breast cancer patients." (PMID 26468334, 2015). "In contrast, neither somatic mutations nor epigenetic silencing of BRCA1 transcription by promoter methylation can fully explain the low level of BRCA1 expression frequently associated with the onset and/or progression of sporadic breast cancer, the most frequent form of the disease." (PMID 25762631, 2015). "Among these, approximately 10% of breast cancer patients have a family history of breast cancer (referred as familial breast cancer), but only 10–15% of familial breast cancer is owing to germline mutations in one of the two high penetrance breast cancer susceptibility genes—BRCA1 and BRCA2." (PMID 25945795, 2015). "TN breast cancer patients harboring the BRCA1 mutations at the time of the diagnosis are younger, have smaller tumor size, and have significantly better recurrence-free and disease-specific survival than TN breast cancer patients with no mutations in the BRCA1 gene." (PMID 25705321, 2015). "Collectively, these results suggest that DNA methylation has a part in low FOXA1 expression in basal subtype breast cancers where BRCA1 is either mutated or depleted, highlighting a role of BRCA1 in promoting FOXA1 expression through suppressing FOXA1 methylation in luminal breast cancers." (PMID 25531315, 2015). "Interestingly, nine of these twelve (9/12, 75.0%) triple negative BRCA1 associated breast cancer cases were found to express at least one of the two TRs." (PMID 26029931, 2015). "Finally, a loss-of-function germline mutation in UBE2T was detected in a high-risk breast cancer patient with wild-type BRCA1/2." (PMID 26085575, 2015). "BRCA1-related breast cancers follow the “two-hits hypothesis”: it implies that both BRCA-1 alleles are altered in the tumor." (PMID 26426992, 2015). "Similarly, selective anti-proliferative effects of BRCA1 or BRCA2 (breast cancer, early onset)-deficient tumors have been demonstrated with olaparib." (PMID 26544897, 2015). "We performed copy number and gene expression profiling to investigate whether CHEK2*1100delC breast cancers harbor characteristic genomic aberrations, as seen for BRCA1 mutated breast cancers." (PMID 26553136, 2015). "BRCA2 mutations are in general less frequent than BRCA1 in younger white women with breast cancer." (PMID 26577449, 2015).
breast cancer (continued). "The product of the HMMR gene, RHAMM, interacts with BRCA1 in the control of mammary epithelial polarization and this function may be at the basis of a modification of breast cancer risk in BRCA1 mutation carriers." (PMID 25830658, 2015). "Breast cancer cell lines were used to determine whether TRs are active in the case of BRCA1 deficiency." (PMID 26029931, 2015). "Interestingly, both of these tumor suppressors, PTEN and BRCA1, have been linked to brain metastasis of primary breast cancers, thus providing an indirect link between miR-20b and brain metastatic breast cancers." (PMID 25893380, 2015). "The majority of BRCA1 mutation breast cancers are of the basal subtype." (PMID 25531315, 2015). "In Finland, recurrent mutations explain most of the familial breast cancer risk caused by the currently known susceptibility genes, such as BRCA1, BRCA2, PALB2, and CHEK2, whereas in other more diverse populations several rare mutations in each gene have been identified." (PMID 25918678, 2015). "Furthermore, several lines of evidences confirmed that the expression pattern of sporadic BRCA1-methylated breast cancers was the same as that of inherited BRCA1 mutations." (PMID 26643130, 2015). "Interest in platinum-based chemotherapy in breast cancer has been renewed, based on the hypothesis of greater susceptibility of triple-negative and BRCA1/2-mutant tumors to DNA-damaging chemotherapy agents." (PMID 26580554, 2015). "Breast cancer risk modifiers in BRCA1/2 mutation carriers have already been identified." (PMID 25925750, 2015). "In particular, we have delineated a sequence of events that is predicted to occur over a substantial subset of R-loop-associated transcriptional pause sites and, when impaired, results in the BRCA1 TR-associated indel mutations observed in BRCA1−/− breast cancer genomes." (PMID 25699710, 2015). "We specifically compared the genomic and gene expression profiles of CHEK2*1100delC breast cancers (n = 14) with BRCAX (familial non-BRCA1/BRCA2/CHEK2*1100delC mutated) breast cancers (n = 34) of the luminal intrinsic subtypes for which both SNP-array and gene expression data is available." (PMID 26553136, 2015). "While germline BRCA1 mutations are rarely found in patients with sporadic breast cancers, the functions of BRCA1 may be inactivated by other mechanisms, which are often referred to as “BRCAness”." (PMID 25769025, 2015). "In other words, alteration of RHAMM function in mammary epithelial differentiation may have a differential effect on breast cancer risk depending on whether it occurs in a BRCA1- or BRCA2-mutated background." (PMID 25830658, 2015). "In the present study, we tested the hypothesis that mitochondrial haplogroups modify breast cancer risk in BRCA1/2 mutation carriers." (PMID 25925750, 2015). "Indeed, the importance of overcoming this pRb-mediated proliferative barrier during cancer progression is supported by the high incidence of RB1 loss or mutations in human breast cancers with inactivated BRCA1 (refs 51, 52, 53)." (PMID 26106036, 2015). "Furthermore, we found double heterozygous breast cancer mutations in two patients with TNBC (one patient was BRCA1/NBN) and two patients with Hn-TNBC." (PMID 26083025, 2015). "For example, HER2/neu gene expression level could be used to predict a patient’s response to breast cancer treatment, while the BRCA1 gene mutation could be used to estimate breast cancer development risk." (PMID 26153774, 2015). "TNBCs constitute approximately 80% of BRCA1-associated breast cancers." (PMID 26083025, 2015). "Also, hierarchical clustering showed a great degree of heterogeneity of copy number profiles amongst the CHEK2*1100delC breast cancers, while BRCA1-mutated breast cancers frequently co-cluster in hierarchical cluster analysis." (PMID 26553136, 2015).